MET (MET proto-oncogene, receptor tyrosine kinase)
Diseases named in the same sentence as MET in open-access papers (continued):
Sharing a sentence is not in itself a finding about the gene and the disease.
cancer (continued). "The HGF/c-MET signaling pathway triggers cell growth and angiogenesis, which are important mechanisms of cancer development, normal growth, and wound healing." (PMID 22438903, 2012). "A second finding from this study is the increase in phosphorylated, activated IGF-1R and MET cell membrane growth factor receptors in CALU-3 cancer cells with acquired resistance to the four TKIs." (PMID 21750552, 2011). "Previous research exhibited that curcumin suppressed NF-κB-regulated proteins control cancer cell progression and these include cyclin D1 and blocked the transactivation of AP-1 on the MET promoter." (PMID 21858220, 2011). "The mechanism by which only certain cells within the c-MET-overexpressing liver develop into cancer is unclear at present, although the presence of a secondary mutation is necessary." (PMID 21949730, 2011). "Third, the level of MACC1 was positively correlated with that of c-MET, which plays critical roles in cancer cell migration and metastasis." (PMID 21955323, 2011). "In our previous studies, we have characterized the conformational landscapes of ABL, EGFR, RET and MET kinases as well as various cancer mutants using MD simulations of the Apo kinase and complexes with ATP and small molecule inhibitors." (PMID 21998754, 2011). "The receptor tyrosine kinases (RTKs) and drug targets EGFR, ERBB2 and MET were each amplified (log2 > 0.6) and overexpressed at the RNA level in one cancer sample." (PMID 21781349, 2011). "A model of rapid progression of polyp to cancer in the presence of MET p.T992I is supported in that individuals with the p.T992I mutation are diagnosed with CRC at an average age of 63 years." (PMID 21970370, 2011). "Although cancer cells harboring amplified MET are initially sensitive to MET TKIs in vitro, they evade this inhibition, despite durable MET inhibition, via reactivation of EGFR and downstream mediators." (PMID 20628489, 2010). "The roles of RET and MET in cancer development and progression are well-known, while the implication of discoidin is a recent finding." (PMID 20955590, 2010). "The improper activation of this program, due to MET deregulated activation, confers proliferative and invasive/metastatic ability to cancer cells." (PMID 20500904, 2010). "The oncogenic nature of RTKs, addiction of cancers to growth signals and given the clustering of c-CBL, EGFR and MET mutations, it is possible that the transforming effect of c-CBL mutations is most likely a combinatorial effect of the three." (PMID 20126411, 2010). "Of special interest is a spectrum of EGFR, ABL, MET, FLT3 and KIT cancer mutations that correspond to the same structurally conserved position in the activation loop, which appeared to be mutated in at least 8 different kinases." (PMID 19834613, 2009). "The rationale for dual-targeting of both EGFR and c-MET besides heterogeneous expression is that an interplay between EGFR and c-MET expression is seen in cancer cells, where therapeutic targeting of one receptor leads to compensatory mechanisms and upregulation of the other receptor." (PMID 41552759, 2026). "Moreover, in BC cell lines, the activation of the HGF pathway through binding of HGF to its receptor c-MET can result in increased cell survival, proliferation, and resistance to cancer inhibitors." (PMID 41597220, 2026). "Overall, these findings suggest that using inhibitors targeting both AXL and c-MET may be a promising strategy for preventing the progression and metastasis of cancers driven by AXL/c-MET signaling." (PMID 39924521, 2025). "Phosphorylation of MET in cancer tissues was downregulated in both cell lines." (PMID 40299447, 2025). "As QSP models of such kind have significant potential in terms of proposing and evaluating new combinations, it is also of great interest to incorporate more therapeutics in addition to small molecule inhibitors but relevant for MET-aberrant cancers in the future versions of the model." (PMID 41368576, 2025).
cancer (continued). "In addition, it was also reported that the pharmacological effect of MET inhibitors on the growth of cancer cells was attenuated under HGF-rich condition, and additional inhibition of inhibitor of HGF-activating proteases overcame the resistance." (PMID 40299447, 2025). "This discovery extends our understanding beyond the well-documented transcriptional regulation of the MET oncogene, shedding light on a novel, post-transcriptional mechanism that cancer cells harness to escalate MET expression in response to environmental stress." (PMID 39774381, 2025). "Aberrant activation of c-MET signaling by MET gene amplification, mutation, or overexpression can lead to migration, invasion, proliferation, neo-angiogenesis within tumors, and metastasis of cancer cells." (PMID 40361420, 2025). "Gene amplification or copy number gain is a commonly reported genomic event leading to MET overexpression and ligand-independent activation, which has been shown to confer transformative potential in various cancers including glioblastoma, NSCLC, colorectal cancer, and medulloblastoma." (PMID 39858062, 2025). "In light of these considerations, we hypothesized that inhibiting the c-MET pathway reduces cancer cell proliferation and migration by modulating downstream signaling pathways." (PMID 41289612, 2025). "All cell lines expressed comparable levels of wild-type MET without gene amplification, despite having diverse mutations or copy number variations in known cancer driver genes." (PMID 39774381, 2025). "Although MET activation by HGF is primarily driven by paracrine signaling from cancer-associated fibroblasts, it has been found that in tumors resistant to gefitinib and erlotinib, MET can also be activated independent of ligand binding." (PMID 40560045, 2025). "It is possible that TAS-115, by inhibiting c-MET and other receptor tyrosine kinases, may alter the signaling interactions between cancer cells and stromal cells, leading to the enhanced survival of NHLFs." (PMID 41289612, 2025). "However, the transcriptional control by factors such as hypoxia-inducible factor or NF-ƙB can only partially explain the pervasive overexpression of MET in cancer, highlighting the need for additional mechanisms supporting the MET oncogene inducible nature." (PMID 39774381, 2025). "Similarly, the kinase inhibitor Merestinib targets the tyrosine kinase receptor MET (hepatocyte growth factor) and is being investigated as a potential anti-cancer therapy candidate." (PMID 41011176, 2025). "Agents targeting HGF/c-MET, including small molecules such as crizotinib, tivantinib and cabozantinib, as well as the antibodies like rilotumumab and onartuzumab, have demonstrated efficacy in various cancers." (PMID 40520181, 2025). "Nevertheless, further studies are needed to define their central role in the collaborative interaction between ETV1/ERG transcription factors and the MET receptor, but for now our results show the ETV1/ERG/MET cooperation in the expression of interesting genes involved in cancer progression." (PMID 39374163, 2025). "Similarly, miR-135b-5p has been linked to the regulation of MET and ADAM12, affecting invasion and proliferation in multiple cancers including PDAC." (PMID 40728965, 2025). "Utilizing the UALCAN database, we assessed MET expression across multiple cancer types." (PMID 41233563, 2025). "On the other hand, hepatocyte growth factor (HGF), produced by cancer-associated fibroblasts (CAFs) and mesenchymal stromal cells (MSCs), triggers the mesenchymal-epithelial transition (c-MET) receptor tyrosine kinase (RTK) predominantly found on c-MET+ cancer cells and MDSCs." (PMID 40281554, 2025).
cancer (continued). "EMI-137 is a 26 amino acid peptide that binds the cell-surface receptor, hepatocyte growth factor receptor (also known as c-MET, mesenchymal–epithelial transition factor), that is upregulated in several cancer types, including thyroid, hepatocellular, colorectal, and gastroesophageal cancers." (PMID 39513952, 2025). "Targeted therapies against MET remain an active area of investigation in oncology research and drug development with numerous clinical trials of MET inhibitors ongoing for MET-aberrant cancers." (PMID 41368576, 2025). "MET is a receptor tyrosine kinase that is related to many cancer types." (PMID 40401526, 2025). "While SVA insertions have been implicated in transcript fusions and alternative splicing in various cancers, no direct association with the MET gene has been reported to date." (PMID 40361420, 2025). "The studies focused on the role of the c-MET RTK in cancer progression and resistance." (PMID 41019287, 2025). "Inhibiting EGFR, VEGFR, and c-MET, whether by single drugs or drug combinations, has proven beneficial by halting cancer cell growth, proliferation, and metastasis although resistance ultimately develops." (PMID 39920140, 2025). "In addition, a correlation between an increased expression of MET in cancer and a poor prognosis has been reported in various human cancers." (PMID 40299443, 2025). "Therefore, HER2 and c-MET are targets for cancer treatments, including targeted therapies and drugs that can also block other proteins, such as EGFR." (PMID 40430804, 2025). "Activation of the HGF/MET signaling axis is known to correlate with cancer progression." (PMID 40299443, 2025). "In addition to MET TKIs, other targeted therapies including inhibitors targeting downstream signaling hub proteins such as MEK, ERK, AKT, and PI3K have also emerged in preclinical investigations and translational studies relating to MET-aberrant cancers." (PMID 41368576, 2025). "Furthermore, gene duplication events leading to an increased copy number of the MET gene can amplify MET protein activation, further exacerbating oncogenic signaling and cancer progression." (PMID 40874416, 2025). "Combinatorial therapeutic approaches targeting both EGFR and MET have been tested clinically—predominantly in the context of EGFR-driven cancers with MET-mediated acquired resistance—and have shown promising results, supporting the benefit of this approach for NSCLC treatment." (PMID 39858062, 2025). "Notably, FDA-approved c-MET inhibitors, such as crizotinib and cabozantinib, have demonstrated enhanced cytotoxicity in ARID1A-deficient cancers, facilitating the translation of these approved drugs for repurposing in ARID1A-targeted precision cancer medicine." (PMID 40369167, 2025). "In addition, more than 40 clinical trials are currently underway investigating the use of Tyrosine Kinase Inhibitor (TKI) and particularly Capmatinib, a specific MET inhibitor, in the treatment of different cancers." (PMID 39374163, 2025). "Some of the MET-inhibitory antibodies display immune-mediated cancer cytotoxicity." (PMID 38892318, 2024). "Moreover, the proportion of c-MET-overexpressing cancers was significantly higher in metastatic sites than in primary BC (p = 0.00002) in HR+/HER2− BC." (PMID 38238761, 2024). "Re-analysis of the TCGA dataset may uncover a notable decrease in MET promoter methylation in cancer patients, indicating transcription activation and increased expression of MET." (PMID 38675409, 2024).
cancer (continued). "Emerging areas include MET inhibitor cabozantinib in combination with an immune checkpoint inhibitor, atezolizumab, which is a monoclonal antibody that works by binding to the protein PD-L1 on the surface of some cancer cells." (PMID 38334610, 2024). "Specifically, MET encodes a receptor tyrosine kinase that is implicated in cell proliferation and frequently overexpressed in various cancers, and HDAC4 (Histone deacetylase 4) influences chromatin structure and regulates cancer proliferation and progression." (PMID 39336170, 2024). "Although these clinical trials did not include patients with BC, c-MET inhibitors might improve the outcome of patients with HR+/HER2− with high c-MET+ CTCs, indicating the presence of cancer cells expressing c-MET." (PMID 38238761, 2024). "This suggests that the efficacy of c-MET inhibition alongside immunotherapy might differ depending on the cancer type." (PMID 39664377, 2024). "Several studies have shown that inhibition of oncoproteins, such as c-MET, may reduce antitumor immunity in various cancers." (PMID 38291041, 2024). "These observational data suggest that cancers with MET alterations could potentially benefit from treatments targeting immune checkpoint molecules (Immune Checkpoint Inhibitors, ICIs)." (PMID 38892318, 2024). "Increased MET expression in the pRCC suggests a unique pathway in cancer development." (PMID 38989164, 2024). "The oncogenic function of MET fusions makes them therapeutic targets for cancers." (PMID 38195556, 2024). "SCR1481B1, a MET inhibitor, is capable of acting on cancers that rely on MET activation." (PMID 39605750, 2024). "Understanding these processes at a molecular level is essential to refine therapeutic strategies that target MET signaling; (ii) the interactions of MET with other membrane proteins and their implications in cancer modulate MET signaling pathways, often amplifying its oncogenic potential." (PMID 39769452, 2024). "In this table, recording the MET mutations characterized by functional studies, subdomain localization of MET mutations were indicated as well as their sensitivity to hepatocyte growth factor (HGF) stimulation and the cancer type in which they were identified." (PMID 38652103, 2024). "Targeting MET presents a promising strategy for developing novel anti-cancer treatments." (PMID 39598385, 2024). "Thus, inhibition of the HGF/MET axis occurring on cancer cells and TME components will revert stroma activation." (PMID 38892318, 2024). "Moreover, several clinical trials have reported the effectiveness of tepotinib and teliso-V in cancers overexpressing c-MET." (PMID 38238761, 2024). "Effective inhibition of cancer cell lines with high c-MET expression was observed." (PMID 39664377, 2024). "This makes the MET-NMDAR complex a promising target for novel anti-cancer therapies." (PMID 39769452, 2024). "Several laboratories have been engaged for about thirty years in the detailed study of an oncogene, identified with the acronym “MET”, that is capable of inducing and supporting the uncontrolled growth of cancer cells and—above all—the invasive and metastatic phenotype." (PMID 38675409, 2024). "Previous studies have shown that withdrawal of MET tyrosine kinase receptor inhibition leads to a post-treatment increase in cancer cell proliferation due to a transient hyper-phosphorylation phase, which culminates in the “MET burst”, i.e., the “flare effect”." (PMID 38675409, 2024). "Notably, numerous studies have demonstrated that the activation of the MET pathway plays a significant role in conferring resistance to cancer treatments, specifically emerging anti-PD-1/PD-L1 immunotherapies." (PMID 39201787, 2024). "Additionally, novel therapeutic strategies targeting MET-driven metastasis and cancer stem cells are discussed, offering insights into innovative approaches to combat MET-related oncogenesis." (PMID 39769452, 2024).
cancer (continued). "Additionally, clinical trials combining c-MET inhibitors with immunotherapies have yielded variable outcomes dependent on factors such as cancer subtype and patient demographics." (PMID 39664377, 2024). "In summary, advancing novel anti-c-MET antibodies presents a promising avenue for cancer treatment." (PMID 39664377, 2024). "MET inhibitors are effective against MET-driven cancers; however, they also pose toxicity concerns." (PMID 38892160, 2024). "Therefore, the activated HGF/c-MET pathway is considered as a negative regulator for cancer immunotherapy." (PMID 38776028, 2024). "Based on our experimental findings and to assess the translational relevance of the MET-E2F1-purine synthesis network described in this study, we obtained from the TCGA database gene expression (RNAseq) and clinical data for four distinct cancer types featuring MET expression." (PMID 38957115, 2024). "It is a key target in cancer research, with trials focusing on inhibiting the MET pathway." (PMID 38790167, 2024). "The second cluster of DEGs, including FGFR2, KDR2 and MET, indicates the importance of key cancer-related pathways, including the PI3K-Akt signaling pathway, EGFR tyrosine kinase inhibitor resistance pathway, Rap1 signaling pathway, Ras signaling pathway, and MAPK signaling pathway." (PMID 38166892, 2024). "Further developing c-MET targeted therapeutic approaches and combining them with current therapies may pave the way for effectively translating novel therapies for NB and other c-MET-driven cancers." (PMID 39458991, 2024). "Moreover, ARGX-111 engaged NK cells to target and kill MET-expressing cancer cells, demonstrating c-MET-specific cytotoxic activity." (PMID 39664377, 2024). "MET overexpression can lead to cancer cell proliferation, survival, and migration." (PMID 39453005, 2024). "Moreover, several studies have shown that inhibiting oncoproteins, such as c-MET, reduces antitumor immunity by promoting PD-L1 expression in various cancers." (PMID 38291041, 2024). "Additionally, activation of HGF/c-MET signaling has been shown to enhance the cancer stem cell properties of NSCLC." (PMID 39201787, 2024). "Moreover, our IHC data revealed that MET+ cancer epithelial cells were closely surrounded by HGF+ fibroblasts, indicating potential communication through the MET‐HGF signalling pathway." (PMID 38445456, 2024). "Hundreds of distinct genetic alterations lead to MET exon 14 skipping in cancers." (PMID 38334610, 2024). "Consequently, the simultaneous targeting of c-MET and PD-L1 with bispecific antibodies has emerged as an effective therapeutic strategy in c-MET/PD-L1 double-positive cancer cells, leading to promising bispecific antibodies." (PMID 39664377, 2024). "Due to the pivotal role of MET in cancer, the use of agents targeting MET is strongly envisaged." (PMID 38892318, 2024). "MET gene was a potential therapeutic target in a lot of cancers, especially in NSCLC." (PMID 37974386, 2024). "Moreover, underlying the plausible importance of MET in onset and/or progression of these cancer types, our TCGA data analysis shows that also MET mRNA levels are increased in these cancer types as compared with the normal tissue mRNA expression levels." (PMID 38957115, 2024). "Given its wide range of influence, the HGF/c-MET pathway has been the focus of numerous studies, aiming to reveal its complexities and the potential implications of its dysregulation in pathological conditions such as cancer, fibrosis, and other diseases." (PMID 38473413, 2024). "And the dysfunction of MET and HGFR is closely related to the poor prognosis of some human cancers." (PMID 37974386, 2024). "However, clinical trials underscore the need for personalized approaches, contingent on cancer type and phosphorylated c-MET status and emphasize that the role of c-MET-targeted therapy in immune cells warrants further exploration." (PMID 39664377, 2024).